MCL1 (MCL1 apoptosis regulator, BCL2 family member)
Diseases named in the same sentence as MCL1 in open-access papers (continued):
Sharing a sentence is not in itself a finding about the gene and the disease.
cancer (continued). "Taken together the underlying mechanisms for the observed markedly promoted growth inhibition and apoptosis induction by combined therapy can be the concomitant suppression of CDK1, CDK9, c-FIP, Mcl-1 and Bcl-2 and upregulation of Bax in cancer cells." (PMID 32375399, 2020). "Owing to MCL1’s positioning in cancer, we initially sought to identify peptides capable of specifically targeting MCL1." (PMID 32111816, 2020). "By contrast, depletion of Pin1 in cancer cells leads to elevated Fbw7 expression, which subsequently reduces Mcl-1 abundance, sensitizing cancer cells to taxol treatment." (PMID 32296699, 2020). "Myeloid cell leukemia 1 (Mcl-1) and B-cell lymphoma 2 (Bcl-2) proteins are promising targets for cancer therapy." (PMID 32260280, 2020). "The development of potent small-molecule inhibitors specific for Mcl-1 have been reported in the literature and, currently, six phase 1 clinical trials are underway for hematological malignancies, among other cancers." (PMID 32751884, 2020). "First, we confirmed using DBP in PDX-isolated cancer cells that vincristine resistance was mediated through MCL-1, correlating with our previous observations in vitro." (PMID 32801295, 2020). "Focal amplification surrounding the MCL1 chromosome region was observed in 10% of various human cancers, promoting pro-survival signals, and preventing cell death." (PMID 33747896, 2020). "According to multiple lines of evidence indicated, MCL1 is commonly up-regulated in various cancers and is considered as a primary factor to resistance the treatment with the BCL2 inhibitor." (PMID 33126914, 2020). "This rationale is supported by recent accounts that knockdown of MCL1 sensitizes cancer cells to cisplatin-induced apoptosis." (PMID 33144577, 2020). "The combination of ABT-199 with MCL1 inhibitors has been studied in other cancers, both in vitro and in vivo, and is currently in clinical trials for patients with AML." (PMID 32764384, 2020). "To further confirm the relationship between RPN2 and MCL1, we analyzed MCL1 expression in the Cancer Genome Atlas (TCGA) database, and found that MCL1 expression was also higher in GBM primary tumors, and positively correlated with the expression of RPN2." (PMID 32404045, 2020). "S63845 is a highly potent MCL1 inhibitor that has exhibited impressive anti-tumor activity across a range of MCL1-dependent cancers, including MM and NHL." (PMID 33198338, 2020). "MCL-1, a member of the Bcl-2 family of proteins, plays an essential role in promoting cell survival and metastasis in many cancers and was discovered to be the key EMT inducer in EC." (PMID 33363153, 2020). "One of the key anti-apoptotic genes involved in c-MYC driven cancer development is Myeloid cell leukemia 1 (MCL1)." (PMID 33187130, 2020). "For example, TKI promotes Mcl-1 degradation and, in combination with Bcl-XL/Bcl2 inhibitors, induced apoptosis in cancer cells." (PMID 32276600, 2020). "Our work identifies MARCH5 as an E3-ligase controlling sensitivity of cancer cells to MTAs by fine-tuning the turn-over of MCL1/NOXA complexes." (PMID 32015503, 2020). "The observed cytostatic effects are in agreement with previous studies showing that STAT3 can protect cancer cells from the apoptotic effects of many individual drugs: STAT3 activity controls the expression of pro-survival genes such as MCL1, BCL2 and BCL2L1." (PMID 32231398, 2020). "Overexpression of one of the anti-apoptotic BCL2 family proteins, MCL1, has been identified as a mechanism utilized by cancers to evade a number of standard chemotherapies, including taxanes, vinca alkaloids, platinum containing compounds, and radiation." (PMID 32111816, 2020). "Several studies have shown that the antiapoptotic protein Mcl-1 is involved in bufalin- or ouabain-induced apoptosis in cancer cells." (PMID 33114727, 2020). "Taken together, compounds with potent activity for eliminating Bcl-2 or Mcl-1 in cancer cells are of great interest as good candidates for targeted therapy." (PMID 32260280, 2020).
cancer (continued). "The amplification and elevated expression of MCL1 has been observed across cancer cell lines and human malignancies." (PMID 32699213, 2020). "In summary, the core biochemical events occurring in all cancer cell lines examined appear to be similar, involving loss of RNA pol II CTD pSer2, MCL1 and induction of apoptosis." (PMID 32645016, 2020). "Mcl-1 is an anti-apoptotic protein, highly expressed in a variety of human cancers and a validated drug target for cancer treatment." (PMID 33322110, 2020). "Mcl-1 is also an anti-apoptotic factor known to be overexpressed in various cancers, including hematologic malignancies." (PMID 33046037, 2020). "Many putative BH3 mimetics were misclassified as direct MCL1 inhibitors, yet they were still able to sensitize cancer cells to other compounds because of their ability to induce NOXA, revealing their therapeutic potential." (PMID 32824203, 2020). "For example, overexpression of MCL1 induces resistance to many widely used anti-cancer therapies drugs such as BCL2 inhibitors, such as paclitaxel, vincristine, and gemcitabine." (PMID 33126914, 2020). "BCL-XL and MCL-1 are anti-apoptotic members of the BCL-2 family which are amplified in diverse cancer types." (PMID 32575557, 2020). "To understand the preponderance of genomic gains of the pro-survival gene MCL-1 in cancer, we analysed genomic data of 24 different cancer entities from The Cancer Genome Atlas (TCGA)." (PMID 32913197, 2020). "Mcl-1, which is indispensable for the survival of multiple cell lineages, is frequently amplified in cancer cells, especially in the context of chemotherapy resistance." (PMID 33046037, 2020). "To examine the functional role of MCL-1 in cancer-cell survival, we treated LUAD cell lines with S6384521, a selective MCL-1 inhibitor." (PMID 32913197, 2020). "Co-culture experiments with CAFs suggest that the increased MCL-1 mRNA expression and protein stability in cancer cells are the result of IL-6 release." (PMID 33308268, 2020). "As an important regulator of apoptosis, Mcl-1 protein, a member of the Bcl-2 family, represents an attractive target for cancer treatment." (PMID 33072738, 2020). "Nevertheless, our current knowledge about the regulation of BCL-2 family members in cancer clearly demonstrates that the efficacy of MCL-1 targeting strategies will depend on 1) the level of apoptotic priming and 2) the MCL-1 dependency status." (PMID 33308268, 2020). "For SAR study, five analogues of RT were synthesized and tested for their anti-cancer and Mcl-1- and Bcl-2-targeting effects." (PMID 32260280, 2020). "On the one hand, the overexpression of BCL2 family members (MCL1 in type I B cells and BCL2 L12 in type III B cells) inhibits perforin and decreases the damage caused by cancer cells." (PMID 32944402, 2020). "Previous studies have revealed that MCL1 degradation plays a central role in taxol or nocodazole-induced apoptosis in cancer cells, and thus the inhibition of MCL1 degradation confers a mechanism of resistance to taxol and nocodazole." (PMID 32486166, 2020). "MCL-1 protein levels correlate with outcome, tumor grade and therapeutic resistance in many cancers including those of the hematopoietic system, breast, lung, and pancreas." (PMID 31735913, 2020). "UMI-77 is an established BH3-mimetic for MCL-1 and was developed to induce apoptosis in cancer cells." (PMID 33184293, 2020). "Considering the short half-life and unstable nature of MCL1, posttranslational regulation, especially by the ubiquitin–proteasome system (UPS), is an important mechanism by which high MCL1 expression is maintained in cancer." (PMID 32699213, 2020). "Myeloid cell leukemia-1 (MCL-1) is one of most frequently amplified genes in cancer due to its role as a survival factor in different kinds of tumors." (PMID 32228680, 2020).
cancer (continued). "Previous studies have shown that MCL1 stabilization confers cancer cells resistance to microtubule targeting agents (MTAs) and functionally extends the lifespan of MTA-triggered mitotically arrested cells." (PMID 32486166, 2020). "Functionally, “osmotic reprogramming” of the tumor environment grants contextual synthetic lethality to BCL-XL inhibitors in dually BCL-XL/MCL-1-protected cancer cells." (PMID 32312973, 2020). "The MCL1 gene is amplified in many human cancers resulting in increased tumor cell survival and chemotherapy resistance." (PMID 32943617, 2020). "Because Bcl-2 inhibitors bind to Mcl-1 with low affinity, Mcl-1 overexpression confers acquired resistance to Bcl-2 inhibitors in multiple cancer types, including non-small cell lung cancer (NSCLC) and acute myeloid leukemia." (PMID 32587776, 2020). "As the first antiapoptotic protein in the Bcl-2 family, Mcl-1 is involved in the apoptosis, differentiation, and cell-cycle regulation of various cancer cells, and it is essential for cancer cell survival and growth." (PMID 32932732, 2020). "As MCL1 promotes drug resistance and overall survival, we propose that NOXA induction is an alternative therapeutic strategy to target MCL1 and either kill cancer cells that are dependent on MCL1 or sensitize cancer cells to other BCL2 inhibitors." (PMID 32824203, 2020). "Among the Bcl-2 family members, Mcl1 appears to be a critical survival factor in several cancer pathologies." (PMID 32731448, 2020). "In various cancer contexts, MCL1-overexpression was described as possible key factor for therapy resistances." (PMID 32999756, 2020). "As Mcl-1 helps cancer cells evading apoptosis, these data encourage further development of RT compounds as well as the design of novel drugs for treating Mcl-1-driven cancers." (PMID 32260280, 2020). "Apoptosis evasion by dysregulation of anti-apoptotic BCL-2 members (BCL-2, MCL-1, BCL-XL) is a common hallmark in cancers." (PMID 32183335, 2020). "This study provides supporting evidence that RT and its simplified right-half model compounds TM-(–)-18 and TM-(–)-4a exert an anti-cancer action through Mcl-1 suppression and in part by the decrease in Bcl-2." (PMID 32260280, 2020). "Mcl-1, an anti-apoptotic member of the Bcl-2 family of proteins, has recently attracted widespread attention due to its potential as a drug target in cancer treatment." (PMID 33322296, 2020). "For certain cancers, cap-dependent translation is essential for the efficient translation of Mcl-1 mRNA." (PMID 32703218, 2020). "Conversely, BCL2, BCL2L2, and MCL1 show downregulation across 2‐3 different cancer types, despite distal BCL2 regulation." (PMID 32419250, 2020). "While the mechanism of overexpression of MCL1 in cancer is not completely understood, USP9X is thought to stabilize MCL1 by removing degradative Lys-48–linked polyubiquitin chains." (PMID 32354135, 2020). "Dysregulation of the anti-apoptotic members BCL-2, BCL-xL and MCL-1 have been widely described in carcinogenesis, cancer progression and chemotherapy resistance." (PMID 32131385, 2020). "Mcl-1 is degraded in cancer cells after effective therapeutic treatment, and defective Mcl-1 degradation is correlated with intrinsic and acquired drug resistance." (PMID 32587776, 2020). "The recent development of novel small molecule compounds has allowed Mcl-1-inhibitory therapy to proceed to clinical trials in cancer treatment." (PMID 33072738, 2020). "In particular, simultaneous targeting of c-FLIP and Mcl-1 has been considered as a promising strategy for anti-cancer research." (PMID 33257694, 2020). "By using a network biology-based approach, we were now for the first time able to derive protein activity of BCL-2, BCL-XL, and MCL-1 in a pan-cancer cohort (NCT/DKTK MASTER cohort)." (PMID 33070156, 2020). "Mcl1 is a primary member of the Bcl–2 family—anti–apoptotic proteins (AAP)—that is overexpressed in several cancer pathologies." (PMID 32731448, 2020).
cancer (continued). "Targeting MCL1 appears to be a promising strategy in cancer therapy, but the development of an effective inhibitor targeting MCL1 has begun only recently." (PMID 32699213, 2020). "Single agent antitumor activity of S1, the BH3-mimetic dual inhibitor of Bcl-2 and Mcl-1, and its derivative B4, has been also reported in cancer models with different origin." (PMID 32455818, 2020). "Mcl-1 is considered a very unstable protein compared to the other Bcl-2 family proteins and the degradation of Mcl-1 can be induced by anti-cancer agents." (PMID 32260280, 2020). "Here, we have compared three compounds reported to be direct inhibitors of MCL1 in cancer cells and assessed their mechanism of action." (PMID 30796196, 2019). "Initial pharmacodynamics data analysis shows dose-dependent reduction of MYC, PCNA, and MCL-1 levels, all being relevant for cancer cell survival." (PMID 31253180, 2019). "S63845 was developed as a potent, selective MCL-1 inhibitor exhibiting low nanomolar cytotoxic activity in multiple cancer models and particularly in hematologic cancers, including AML." (PMID 30813354, 2019). "Then, we observed that miR-101 target genes (c-Fos, ZEB1 and Mcl-1) known to promote cancer progression were significantly downregulated in AML cells with SNHG1 knockdown." (PMID 31615767, 2019). "These CM-induced MCL-1 expression at both mRNA and protein level in ZR-75-1 cells and this induction was maintained when cancer cells were challenged by ABT-737." (PMID 30631150, 2019). "In this context, B-cell lymphoma 2 (BCL-2) family proteins, notably myeloid cell leukemia-1 (MCL-1), are known for their role in both the development and persistence of AML, and are often associated with cancer-cell survival and resistance to chemotherapy." (PMID 30815228, 2019). "MCL-1 is a critical cell survival factor for cancer and contributes to chemotherapy resistance by directly affecting cell death pathways." (PMID 30815228, 2019). "In fact, amplification of the MCL-1 gene is one of the most frequent somatic genetic events in human cancer, providing evidence of its central role in the pathogenesis of malignancy." (PMID 30815228, 2019). "Disruption of the normal apoptotic function is often observed in cancer, where cell death is avoided by the overexpression of anti-apoptotic proteins of the Bcl-2 (B-cell lymphoma 2) family, including Mcl-1 (myeloid cell leukaemia 1)." (PMID 31692474, 2019). "Metformin in combination with TRAIL induced the dissociation of Noxa from Mcl-1 followed with an increased E3 ligase Mule activity that promoted polyubiquitination of Mcl-1 in the cancer cells." (PMID 31831021, 2019). "Cells with overexpression of anti-apoptotic proteins in the Bcl-2 family such as Bcl-2, Bcl-XL, and Mcl-1 in cancer cells are considered to be “less primed” to apoptosis and are associated with poor prognosis." (PMID 31092272, 2019). "Overexpression of Mcl-1 induces oncogenic transformation, and increased expression of Mcl-1 protein is found in the majority of human cancer including NSCLC." (PMID 31601252, 2019). "Recently, compound S63845 was demonstrated to be a more potent inhibitor of MCL1 that induced tumor regressions in various mouse cancer models." (PMID 30796196, 2019). "Approximately 10% of all cancers show a focal amplification of chromosome 1q21.2, a region harboring the antiapoptotic gene MCL1." (PMID 31266530, 2019). "Based on these premises, we measured MCL-1 expression changes in luminal cancer cells upon addition of bCAFs -CM." (PMID 30631150, 2019). "Increasing evidence suggests that Mcl-1 plays an essential role in cancer cells, as Mcl-1 expression levels are often increased in cancer." (PMID 31349793, 2019). "Anti-apoptotic proteins, Bcl-2 and Mcl-1 have been studied extensively, given their ability to induce chemo-resistance in different cancers, including AML." (PMID 31466259, 2019).
cancer (continued). "More recently, the role of Bcl-xL and Mcl-1 as key determinants of cancer cell response to E7107 was shown in a large series of cancer cell lines, including NSCLC cells." (PMID 31134126, 2019). "Mcl-1 is widely expressed in normal human tissues and is abnormally highly expressed in many malignant tumor tissues." (PMID 30738430, 2019). "For example, the combination of the BCL-2 inhibitor and MCL1 inhibitor was synergistic when cancer cells were either dependent on MCL1, or the BCL-2 family contributed to the emerging resistance." (PMID 31370269, 2019). "Because BCL-2 and BCL-xL inhibitors fail to target MCL-1, MCL-1 expression is an obvious potential mechanism by which cancer cells resist treatment with ABT-263, and this mechanism has been demonstrated in some cancer models." (PMID 30728900, 2019). "Collectively, we conclude that targeted therapies create a new dependence on MCL-1 in multiple cancer types and in primary tumors." (PMID 31727958, 2019). "As Mcl-1 is critical for cancer cell survival and chemotherapeutic failure, this novel information regarding the Mcl-1-targeted compound would be beneficial for the development of efficient anti-cancer strategies or targeted therapies." (PMID 31117253, 2019). "Together these findings suggest that the EGFR is essential for maintaining growth and preventing apoptosis in cancer cells, and up-regulation of MCL-1 is an important mechanism through which EGFR functions." (PMID 31150457, 2019). "By targeting MCL1 for ubiquitination and degradation, or by knocking it down, cancer cells are highly sensitized to chemotherapy drugs." (PMID 31467488, 2019). "Further, we monitored the levels of the Mcl-1-Ubiquitin complex and found that the formation of the complex dramatically increased in the RT-treated cancer cells." (PMID 31117253, 2019). "As an adjuvant therapy, co-administration of HSP90 inhibitor, NVP-AUY922, with ABT-737, BCL-2 inhibitor, enhances the anti-cancer effect of ABT-737 by targeting MCL-1 protein that grants the cancer resistance to ABT-737 in small cell lung cancer." (PMID 31878360, 2019). "Mcl-1 is a relatively unstable protein, and the degradation of Mcl-1 can be induced by certain anti-cancer drugs." (PMID 31117253, 2019). "In this study, we confirm a high binding affinity and selectivity of S63845 to induce apoptosis in MCL-1-dependent cancer cell lines." (PMID 30185825, 2019). "Previous studies have shown that miR-615 can increase the level of Mcl-1 protein and promote the proliferation and metastasis of cancer cells and the ability of antiapoptosis by inhibiting the expression of CELF2 in cancer cells." (PMID 31885571, 2019). "Many cancers engage mechanisms for stabilization of MCL-1, which is a highly unstable protein that exhibits rapid turnover due to proteasomal degradation." (PMID 31405035, 2019). "In this study, we show that the orally bioavailable XPO1 inhibitor KPT-330 reduced Mcl-1 protein level, by which it synergized with Bcl-xL inhibitor A-1331852 to induce apoptosis in cancer cells." (PMID 31113936, 2019). "EGFR, ERBB3, MMP20, MMP27, MCL1, BCL2A1 and BAK1 appear to be important genes for cancer progression due to their frequent association with recurrent cancer-related genes in women." (PMID 31205821, 2019). "And DMP micelles were used to deliver Bcl-xl siRNA and Mcl1 siRNA into C26 cells for anti-cancer activity study in vitro." (PMID 31165329, 2019). "Recent evidence has suggested that the survival of human cancers is likely to be dependent on expression levels and function of the myeloid cell leukemia 1 (Mcl-1) protein." (PMID 31117253, 2019). "Mcl-1 is an antiapoptotic protein of the Bcl-2 family that is essential for the survival of multiple cell lineages and is highly amplified in human cancer development." (PMID 31073529, 2019).